IFNG (interferon gamma)
Diseases named in the same sentence as IFNG in open-access papers (continued):
Sharing a sentence is not in itself a finding about the gene and the disease.
infection (continued). "Unstimulated jej-LP explants of piglets from DON sows showed a significantly higher gene expression for IFNγ at PND10 demonstrating that maternal exposure to this mycotoxin can produce conditions for polarization of Th1 responses increasing piglet protection against intracellular pathogen infection." (PMID 32708852, 2020). "However, ASF-colonized mice showed slight increase of Ifnγ expression upon infection." (PMID 31396223, 2019). "However, we observed comparable viral loads and IFNγ response of T cells on day 16 post-infection between NKp46-Cre-Il10fl/fl mice and their control littermates, demonstrating that NK cell-derived IL-10 is dispensable in establishing immunosuppression in the salivary gland during MCMV infection." (PMID 31803193, 2019). "Interferon-gamma (IFN-γ) and tumor necrosis factor (TNF) -α and -β, from the Th1 profile, are known to be involved in the resistance and elimination of the parasites, while Th2 cytokines such as IL-4 and IL-10 are linked to susceptibility to infections by Leishmania." (PMID 31131262, 2019). "However, peptide 260 and 451 elicited the highest frequency of IFNγ+ T cells in splenocytes from CHKVf5 vaccinated mice indicating that vaccine-induced responses were skewed toward infection-associated, non-dominant epitopes." (PMID 31736977, 2019). "Interestingly, the IFNγ secretion profile in the vaccine 1 and two control groups (i.e., control and adjuvant groups) showed a bimodal response with a first peak of IFNγ secretion at D61 (7 days post infection) followed by a second peak at D96 (42 days post infection)." (PMID 31620134, 2019). "We then wanted to experimentally support cell–cell signaling between NKT cells, IFNγ secretion, and activation following infection of a monocyte subset in WT individuals as suggested by the dynamic deconvolution, and link it to overall infection outcome between WT and TLR10 individuals." (PMID 31332193, 2019). "This difference in IFNγ response might explain the different ability of the two vaccines to prevent the dissemination of the parasite DNA from the intestinal tissues to the other organs upon challenge infection." (PMID 31620134, 2019). "It will be of interest to determine whether circulating memory CD8+ T cells use cytolysis as the primary mechanism to control other intracellular pathogens in non-lymphoid tissues or if the production of cytokines (e.g. IFNγ, TNFα) is required to protect against some types of infections." (PMID 30875408, 2019). "The different kinetics of IFNγ production in the vaccine 2 group might be explained by the broader antigenic range of vaccine 2, resulting in T. gondii-specific antibodies and T cells which might have controlled the parasite at the initial site of infection." (PMID 31620134, 2019). "A genome-wide association study of children in Malawi and Kenya found that STAT4 polymorphisms were associated with an increased risk of non-typhoidal salmonella, which was related to low IFNγ production by NK cells and decreased NK cell responsiveness to IFNγ during infection." (PMID 31417545, 2019). "Because unified CCVs were observed in IFNγ-treated cells, which is a phenotype requiring the effector protein Cig2, it is likely that C. burnetii are initially capable of translocating early effector proteins in cells that were treated with IFNγ 6h after infection." (PMID 31461509, 2019). "Furthermore, Th1/Th2 balance can be evaluated by the ratio of their polarizing cytokines (i.e., IFNγ/IL4), and animals with imbalanced Th1/Th2 response may be more susceptible to certain kinds of infections." (PMID 30936878, 2019). "We also observed more IFNγ-producing non-γδ T cells in coinfected compared to singly-infected ears at days 1 and 7 p.i., which may implicate innate lymphoid cells at the infection site early during coinfection." (PMID 31107882, 2019).
infection (continued). "Moreover, since γδ T cells are early producers of cytokines such as IL-17 and IFNγ in several infection models, increased retention of γδ T cells in a LN might also contribute to rapid innate responses against infections." (PMID 29895956, 2018). "However, the levels of IFNγ, IL-4 and IL-5 were elevated in Stat2−/− mice during super-infection." (PMID 30337919, 2018). "That VIP is protective in vitro, suggests that the decreased levels of VIP occurring in the colonic epithelial cells during infection may lead to that the infection induced expression of TNFα and IFNγ inflict even greater damage than what might have occurred otherwise." (PMID 30252907, 2018). "Thus, during RHVP infection, surface pQa-1 levels could be correlated with the infection-induced IFNγ production even when TAP function is impaired." (PMID 30575523, 2018). "The importance of IFNγ in control of MABS infection is highlighted in a recent case-control study from Thailand in which MABS was found to be the most common NTM clinical isolate, and the presence of anti-IFNγ autoantibody was strongly associated with disseminated infection." (PMID 30443245, 2018). "Interferon-gamma (IFN-γ), tumor-necrosis factor, neutrophils, and other phagocytic cells play important roles in protection against F. tularensis infection, although they may be most critical during primary infections." (PMID 29922267, 2018). "However, it produced an enhanced infection in IFNγ-activated macrophages and in both heart parasitism and the peak of parasitemia in mice, suggesting that when the immune system is activated in vivo, peroxynitrite production is probably an important mechanism of parasite killing." (PMID 29672619, 2018). "Therefore, we wondered if C. trachomatis had a mechanism by which it could attenuate the effects of IFNγ secreted by immune cells in response to a primary infection." (PMID 29855501, 2018). "Finally, paralleling previous observations during influenza infection, recent work in the P. berghei mouse model demonstrated a role for γδ T cells in increasing levels of antigen-specific antibodies, Tfh cells, and germinal center B cells via expression of IL-21 and IFNγ early in infection." (PMID 30405634, 2018). "However, lower parasite loads were found in cotyledons from ewes that gave birth in G3 (103, IV), which, along with lower IFNγ levels detected, could suggest mild infection in these animals." (PMID 29739449, 2018). "Furthermore, we found that MAIT cells can produce IFNγ in response to in vitro infection with ZIKV." (PMID 29357366, 2018). "However, the single infections did induce IL-4, similarly to that described for IFNγ (p < 0.05)." (PMID 29942312, 2018). "Furthermore, IFNγ levels in this early phase of infection partially condition the subsequent adaptive immune response by inducing IDO-dependent tolerogenic DCs, which subsequently activate tolerogenic Treg that produce IL-10 and TGFβ, inhibit Th2 cells, and prevent fungal allergy." (PMID 29371571, 2017). "Our data suggest that increased expression of IFNG and related pathways in females may contribute to the observed differences in tissue responsiveness (TP and TS) between the sexes in the context of equal infection exposure." (PMID 28966918, 2017). "Thus, CD4+ T cell-dependent myeloid infection control could have reflected either that only CD4+ T cells efficiently recognized infected myeloid cells (via MHC II), or that only IFNγ was able to control their infection." (PMID 28394921, 2017). "Thus, it could be that IFNγ-induced ROS production in Lm-infected hMDDC was to low to see significant effects of IFNγ neutralization on infection rate in our in vitro model." (PMID 29312350, 2017). "Furthermore, also the only mouse of the isotype-treated CD4+IFNγ-/- T cell recipient group that died upon infection on day 16 had only very low amounts of bacteria predominantly in the liver (52.0 copies) followed by the brain (20.8 copies), lung (6.49 copies) and spleen (1.01 copies)." (PMID 28222146, 2017).
infection (continued). "Moreover, C57BL/6 RAG2−/−γc−/− mice that lack not only T and B cells but also NK cells produce reduced serum levels of IFNγ and develop enhanced bacterial burden and liver pathology in the infection with R. conorii compared to NK cell-competent C57BL/6 RAG2−/− mice." (PMID 28770333, 2017). "Using Nakayama strain of JEV it has been shown that IFNγ-null mice are more susceptible to infection than WT B6 mice, unlike our observations and this may be due to differences in the virulence of the strains used." (PMID 28151989, 2017). "Data from studies of infection with L. monocytogenes in mice indicate that treatment with hLf displayed significant effects on one main organ target of this pathogen in regards to bacterial colonization, necrosis, and mRNA expression of pro-inflammatory cytokines TNFα, IL-1β and IFNγ." (PMID 28257033, 2017). "Also infection rate tendentially correlated inversely with IFNγ release (r = −0.79)." (PMID 29312350, 2017). "In contrast, all CD4+IFNγ-/- T cell recipients whether treated with isotype antibody or anti-IL-17A were negative for R. typhi in the organs when the experiment was terminated on day 26 post infection." (PMID 28222146, 2017). "However, at an early stage of infection, the individual ability to produce IFNG may determine the outcome of the disease toward mycobacterial clearance versus chronic infection." (PMID 29046669, 2017). "However, there was an improvement in parasite control 72h post-infection in the presence of IFNγ, suggesting that Fzd6-/- bone marrow macrophages could partially contribute to the decreased parasite burden." (PMID 28787450, 2017). "GFAP levels were elevated significantly with infection in CD46+ mice, but not in CD46+/IFNγ-KO mice, in comparison to uninfected controls at 7 dpi, suggesting that localized reactive astrogliosis may be occurring in the hippocampus in the presence of IFNγ during infection." (PMID 27178303, 2016). "Several reports have shown that IFNγ- or iNOS-deficient mice that were infected with M. tuberculosis die quickly and exhibit uncontrolled M. tuberculosis growth, indicating that IFN-γ is an essential component to activate the immune responses that limit M. tuberculosis growth following infection." (PMID 27148227, 2016). "Therefore, to verify whether there were differences in the level of IFNγ produced by cNK cells at day 5 post infection with the different parasite strains, we purified cNK cells from infected animal PEC and spleen by negative selection." (PMID 27721814, 2016). "In our study, erythroid hypoplasia was more evident in the co-infectedgroup, which may be also explained by a synergic effect of both infections oroverproduction of interferon-gamma and tumour necrosis factor-alpha in the course ofco-infection, as described by others." (PMID 27074255, 2016). "However, high levels of IFNγ have been reported to be protective against infection with S. mansoni." (PMID 26540410, 2015). "Early during infection (day 7, 1-2% parasitaemia), spleens showed disruption of germinal centre architecture with heavy B-cell activation (centroblasts), and splenocytes showed increased expression of IFNγ, IL6 and IL12 upon in vitro stimuli by P. falciparum-parasitized red blood cells (pRBC)." (PMID 25890318, 2015). "While the cellular levels of these factors vary between genetically divergent individuals and are known to contribute to the differential response to infection, the genetic loci that predispose macrophages to either the M(IFNG) or M(IL-4) phenotypes are not known." (PMID 26510153, 2015). "Notably, in in vitro studies IFNγ promoted the infection of astrocytes by HIV." (PMID 25695249, 2015). "Thus, subsequent studies solely focused on the impact of IFNγ on infection." (PMID 26562011, 2015). "Additionally, IFNγ disrupts the endothelium, which may contribute to endothelial barrier leakage and pathology in infection." (PMID 26512687, 2015).
infection (continued). "Indeed, our data support that microglial cells may contribute to IFNγ production in the CNS in chagasic infection." (PMID 25695249, 2015). "Indeed, humans or mice lacking Ifnγ or its receptor are highly susceptible to infections by less virulent intracellular pathogens." (PMID 26029930, 2015). "Finally, as IFNγ potently activates T cell responses through enhancement of phagocytosis and antigen presentation, such stimulation of antigen presentation would be predicted to enhance adaptive immune responses to in vivo infection." (PMID 26562011, 2015). "Indeed, anti-TNF completely prevented the IFNγ-enhanced infection of astrocytes by T. cruzi." (PMID 25695249, 2015). "However, key regulators of macrophage migration in response to infection are LPS and IFNγ." (PMID 25719758, 2015). "Indeed, we found that pICLC treatment did not rescue IFNγ deficient mice as the animals succumbed to infection at the same rate as untreated controls." (PMID 26252005, 2015). "Activated Th cells are more susceptible to infection, as are Th17 cells (defined by the production of IL-17), Th1 cells (produce IFNγ) and Th22 cells (produce IL-22 in the absence of IL-17 or IFNγ)." (PMID 26335139, 2015). "Therefore, we tested whether IFNγ directly enhanced astrocytes infection by T. cruzi or whether this effect depends on TNF induction." (PMID 25695249, 2015). "Thus, if indole is present at a sufficient concentration in the infection microenvironment, genital serovars could circumvent the bactericidal/bacteriostatic effects of IFNγ." (PMID 24918090, 2014). "Moreover, deficiency in IFNγ has been associated with high mortality and lack of viral clearance upon infection with MCMV, emphasizing its important role in protection against MCMV induced lethality and pathogenesis." (PMID 25473962, 2014). "However, Itk−/− mice can secrete IFNγ in response to innate stimuli, such as IL-12/IL-18, perhaps this may explain the apparent Th1 sparing reported in some infection studies." (PMID 25250764, 2014). "Similarly, the gene encoding type II interferon (i.e., IFNG) was also upregulated at 6 and 24 hpi following M. bovis infection, but was not DE at any post-infection time point following infection with MAP and M. bovis BCG." (PMID 25414700, 2014). "Thus we hypothesized that Delta-24-RGD infection enhances the presentation of TAAs to CD8+ T cells either through IFNγ stimulation or by the infection itself." (PMID 24827739, 2014). "During infection, IFNγ may trigger MSCs in the bone marrow to secrete elevated levels of Shh." (PMID 24069395, 2013). "However, in a study on cattle experimentally infected with MAP, a proportion of animals were misclassified as TB reactors using the IFNγ test at different time points post-infection, including one animal that was misclassified at 44% of the sampling time points." (PMID 24308747, 2013). "The fold increase in cytokine responses was generally higher in the CA/09 responses; for example the median IFNγ+ response against CA/09ni vdiff peptides was ∼200-fold higher in the infected versus pre-2009 group, whereas the response against NC/99ni peptides was ∼5-fold higher after infection." (PMID 23526940, 2013). "Thus, we determined the functionality of the epitope-specific CD8 T cells in the three groups of mice by intracellular cytokine staining (ICS) for the presence of IFNγ- and/or TNFα-producing cells and calculating the ratio of IFNγ+TNFα+/IFNγ+ cells at days 7 and 13 post infection." (PMID 24391647, 2013). "In the present study, we genotyped SNPs of TNF, IFNG, IL6, IL10, and TGFB1 which are multifunctional cytokine that have been implicated in inflammation, immunity, and cellular organization and have been proposed to play important roles in infection and cancer biology." (PMID 23936772, 2013).
infection (continued). "The only factors shown to induce super-shedder status so far have been antibiotic-mediated ablation of the gut microbiota or neutralization of IFNγ cytokine.The immune processes pivotal in the establishment of the super-shedder state may take place at the onset of infection." (PMID 23754944, 2013). "However, in certain murine strains, IL-4 deficiency was not enough to drive substantial increases in IFNγ production or to completely prevent development of a TH2-type response during infection." (PMID 23429492, 2013). "This expression could be the direct result of viral or other infections of thyroid epithelial cells, or it may be induced by cytokines such as interferon-gamma produced by T cells that have been attracted to the gland either by an infection or directly because of the presence of thyroid antigens." (PMID 23878745, 2013). "The reconstitution of naïve cd8−/− mice with CD8+ cells from ifnγ−/−pfn+/+ mice (deficient in IFNγ but able to express Pfn) prior to infection had no impact on electrical conduction, which were similar to those found in NR cd8−/− mice, but aggravated cardiomyocyte injury." (PMID 22532799, 2012). "Although our results would appear to suggest that T1IFNs do not contribute to control of malaria infection, we considered the possibility that the redundancy between T1IFNs and IFNG in the regulation of ISG expression could confer redundancy in control of infection." (PMID 23144737, 2012). "Given the capacity of SM iNKTs to produce IFNγ, TNFα, IL-2, IL-13, and IL-10 and to degranulate in response to αGalCer stimulation, the authors speculate that iNKTs may play a role in controlling immune activation in this model of natural infection." (PMID 22916008, 2012). "Interestingly, in the presence of robust IL-27 expression we also observed a greater induction of IL-10 in the serum of IL-27-expressing mice by day 7 post-infection compared to control or p28-expressing mice, while systemic IFNγ protein was similar between all groups." (PMID 22479310, 2012). "We hypothesized that this delay in growth restriction might correlate with the amount of time that it would take for full transcriptional or post-transcriptional activation of important antimicrobial genes that require both IFNγ and a signal transmitted to the cell following infection." (PMID 22912573, 2012). "In addition, IFNγ, TNFα, and IL1β were also increased under infection." (PMID 21869919, 2012). "Furthermore, these results suggest that IFNγ may play a greater role in intestinal tissue injury while TNFα may be more involved in the systemic manifestations of infection." (PMID 23217055, 2012). "However, at this time point, the IFNγ levels in the culture supernatant of cells isolated from the two groups fed with the probiotic strain (Lc-S and Lc-S-Lc groups) decreased significantly (p < 0.01) compared to the infection control (S)." (PMID 21813005, 2011). "Intracellular staining for IFNγ revealed that the frequency and absolute number of CD4+ T-cells producing the cytokine upon re-stimulation with C. pneumoniae were higher in TLR2/4 double-deficient when compared to wild type mice especially day 9 post infection." (PMID 22096480, 2011). "As an additional test for our hypothesis that IFNγ signaling acts on HSCs during infection, we performed competitive reconstitution assays, using purified LSK cells obtained from wild type (EGFP-transgenic, GFP+, CD45.2+) and IFNγR-deficient mice (GFP−, CD45.2+)." (PMID 22194881, 2011). "As regard to the release of IFNγ to the intestinal fluid, the administration of the probiotic bacteria maintained the levels of this cytokine similar to the basal data, at difference of the S group, which showed a significant decrease of IFNγ concentration after infection." (PMID 21813005, 2011).